DOCK11 (dedicator of cytokinesis 11)
Description:
Guanine nucleotide-exchange factor (GEF) that activates CDC42 by exchanging bound GDP for free GTP. Required for marginal zone (MZ) B-cell development, is associated with early bone marrow B-cell development, MZ B-cell formation, MZ B-cell number and marginal metallophilic macrophages morphology (By similarity). Facilitates filopodia formation through the activation of CDC42.
Synonyms: ACG; ZIZ2; FLJ32122; FLJ43653; ADMIDX; bB128O4.1
Tractability: PROTAC: ubiquitination databases record sites on it; its protein half-life has been measured.
Gene: Protein-coding gene on chromosome X (118,495,814 to 118,686,974, forward strand). Ensembl gene ENSG00000147251.
Pathways (Reactome):
Signal Transduction: CDC42 GTPase cycle; RAC1 GTPase cycle
Hemostasis: Factors involved in megakaryocyte development and platelet production
Gene Ontology:
Molecular function: protein binding; guanyl-nucleotide exchange factor activity; small GTPase binding
Biological process: positive regulation of filopodium assembly; B cell homeostasis; marginal zone B cell differentiation; positive regulation of GTPase activity; regulation of Rho protein signal transduction; small GTPase-mediated signal transduction
Cellular component: cytosol
Gene-disease validity (ClinGen):
ClinGen rates the evidence that DOCK11 causes each of these diseases.
autoinflammatory disease, multisystem, with immune dysregulation, X-linked (X-linked): Strong.
Homologues: Orthologues: chimpanzee DOCK11 (99% identical), macaque DOCK11 (99% identical), rabbit DOCK11 (98% identical), guinea pig DOCK11 (97% identical), mouse Dock11 (97% identical), rat Dock11 (96% identical), pig DOCK11 (96% identical), dog DOCK11 (96% identical), tropical clawed frog dock11 (77% identical), zebrafish dock11 (64% identical), Drosophila melanogaster Zir (29% identical), Caenorhabditis elegans F46H5.4 (23% identical), and 1 more. Paralogues in human: DOCK9 (60% identical), DOCK10 (51% identical), DOCK7 (31% identical), DOCK6 (31% identical), DOCK8 (30% identical), DOCK3 (16% identical), DOCK5 (16% identical), DOCK1 (15% identical), DOCK4 (15% identical), DOCK2 (15% identical).
Diseases named in the same sentence as DOCK11 in open-access papers:
DOCK11 is named in the same sentence as 24 diseases in open-access papers, as found by Europe PMC text mining. Sharing a sentence is not in itself a finding about the gene and the disease. The quoted sentences say what the papers report.
Autoimmunity (2 papers, 2023 to 2025). The occurrence of an immune reaction against the organism's own cells or tissues. "DOCK11 deficiency in patients with X-linked actinopathy and autoimmunity." (PMID 37848930, 2023). "This case reinforces the importance of including DOCK11 in next-generation sequencing panels when evaluating pediatric patients with unexplained systemic inflammation, early-onset autoimmunity, or atypical cytopenias." (PMID 41250716, 2025).
chronic hepatitis B (2 papers, 2023 to 2024). "We also found that DOCK11 levels in liver biopsies from patients with chronic hepatitis B were significantly reduced by entecavir (ETV) treatment, and this reduction correlated with HBV surface antigen levels." (PMID 38793626, 2024). "We also analyzed a publicly available dataset on human liver tissue (GEO: GSE83148) and found that the expression of DOCK11 in hepatocytes was influenced by HBV infection and was increased in patients with chronic hepatitis B." (PMID 37243264, 2023).
hepatocellular carcinoma (2 papers, 2024 to 2026). A malignant tumor that arises from hepatocytes. "Using a minicircle HBV cccDNA reporter, we observed that luciferase activity declined significantly in DOCK11-depleted hepatoma cells over time, consistent with impaired cccDNA maintenance." (PMID 42300748, 2026). "Human hepatocellular carcinoma cell line Huh7 and mouse primary hepatocytes were transfected using these gapmers, and the inhibition of DOCK11 expression was evaluated 48 h after transfection." (PMID 39109217, 2024). "Previous single-cell gene expression analyses identified the dedicator of cytokinesis 11 (DOCK11) as a host factor in HBV-infected hepatoma cells, which is involved in the maintenance of cccDNA." (PMID 39109217, 2024).
autoinflammatory syndrome (1 paper, 2025). A group of disorders of the innate immune system characterized by attacks of seemingly unprovoked inflammation without significant levels of either autoantibodies or autoreactive T cells more characteristic of autoimmune disease. "DOCK11 deficiency exemplifies the diagnostic challenges associated with novel monogenic autoinflammatory syndromes." (PMID 41250716, 2025). "Furthermore, the co-occurrence of pathogenic variants in both DOCK11 and UNC13D in this patient underscores the potential complexity of genetic contributions to autoinflammatory syndromes and the value of comprehensive genetic evaluation in diagnostically challenging cases." (PMID 41250716, 2025).
COVID-19 (1 paper, 2025). A disease caused by infection with severe acute respiratory syndrome coronavirus 2. "Homozygous and hemizygous DOCK11 deficiency has also been newly associated with hyper-inflammatory states, but whether DOCK11 mutations contribute to CSS or severe COVID-19 is currently unknown." (PMID 40872807, 2025).
hemophagocytic lymphohistiocytosis (1 paper, 2025). "Our report highlights the need for increased awareness of DOCK11 deficiency among clinicians and researchers, especially considering its clinical overlap with other inborn errors of immunity, such as hemophagocytic lymphohistiocytosis." (PMID 41250716, 2025).
immunodeficiency disorders (1 paper, 2023). "DOCK11 dysregulation has been linked to immunodeficiency disorders." (PMID 37026480, 2023).
pancreatic cancer (1 paper, 2022). "We adopted R package to plot the Forest plot of this model, and found that the P values of ERAP2 and DOCK11 were both less than 0.05, suggesting that they could be independent prognostic factors for pancreatic cancer patients treated with gemcitabine, respectively." (PMID 36214762, 2022).
Seizure (1 paper, 2025). A seizure is an intermittent abnormality of nervous system physiology characterized by a transient occurrence of signs and/or symptoms due to abnormal excessive or synchronous neuronal activity in the brain. "Seizures, while not classically reported in DOCK11 deficiency, were observed in our case." (PMID 41250716, 2025).
shigellosis (1 paper, 2021). Shigellosis is a bacterial infection leading to dysentery and is caused by Shigella, which are small, ubiquitous Gram-negative bacteria belonging to the enterobacteria family. "A KEGG pathway of 13 genes associated with DOCK11 revealed an association with “Focal adhesion”, “Regulation of actin cytoskeleton”, “Bacterial invasion of epithelial cells”, and “Shigellosis” as four areas in which the generation of the cytoskeletal protein actin is suppressed." (PMID 33539396, 2021).
Splenomegaly (1 paper, 2025). Abnormal increased size of the spleen. "Our patient’s clinical picture, recurrent fever, mild splenomegaly, systemic inflammation, and elevated proinflammatory markers (IL-1β, IL-6, serum amyloid A), aligns with the phenotype of patients exhibiting complete loss of DOCK11 expression." (PMID 41250716, 2025).
cancer (4 papers, 2017 to 2024). A tumor composed of atypical neoplastic, often pleomorphic cells that invade other tissues. "The closely related DOCK11 and DOCK10, belonging to the same subfamily, exhibit 66% identity and 83% similarity in the DHR2 domain, suggesting their potential involvement in promoting cancer cell migration and infiltration through the activation of CDC42 or other GTPases." (PMID 38793626, 2024). "Six of the 10 remaining genes, despite not being listed, were genes for which literature search supported undeniable oncogenic properties (STIM2, ARHGAP24, KLF12, KMT2C, CCDC88C and DOCK11), and 4 genes were—to our knowledge—not previously reported in cancer, yet may include new candidate drivers." (PMID 28534499, 2017).
tumor (4 papers, 2015 to 2024). "Accordingly, bulk RNAseq analysis from tumor tissues unveiled a down-regulation of several genes that are related to B cell activation in CoPEC-positive tumors, such as CD19, CCR6, CD40LG and DOCK11." (PMID 38417029, 2024). "DOCK11 showed significantly lower levels in tumor datasets, while MCAM, MYO10, and WASF3 exhibited significantly higher levels in tumor datasets, compared with the normal group." (PMID 34128858, 2021).
infection (3 papers, 2012 to 2024). The state of being infected such as from the introduction of a foreign agent such as serum, vaccine, antigenic substance or organism. "DOCK11, DIDO1 and DMXL2 were only found in leukocytes during infection with the EuA lineage: these are associated with innate immunity and inflammation activation." (PMID 34141493, 2021). "The hetero-gapmer scramble and DOCK11#1 were separately injected 10 and 25 days after AAV8-HBV1.3mer infection for analyzing the early and chronic phases of infection." (PMID 39109217, 2024). "In cell culture experiments with HBV infection, DOCK11 showed GEF-mediated activation of CDC42 and ADP-ribosylation factor 1, further promoting viral replication by facilitating infection from HBV virion entry to nuclear translocation." (PMID 39109217, 2024). "SAT2, DOCK11 and MMP14 were found in both infection and clearance states of Mtb but were not present in control cells." (PMID 34141493, 2021).
DOCK11 also shares sentences with these, for which no sentence is quoted: Obesity (2 papers); breast tumors (1); Cirrhosis (1); coronary atherosclerosis (1); glioma (1); infectious disease (1); ischemic heart disease (1); primary immunodeficiency (1); T-cell lymphoma (1); X-linked multisystem autoinflammatory disease with immune dysregulation (1).